BATF (basic leucine zipper ATF-like transcription factor)
Description:
AP-1 family transcription factor that controls the differentiation of lineage-specific cells in the immune system: specifically mediates the differentiation of T-helper 17 cells (Th17), follicular T-helper cells (TfH), CD8(+) dendritic cells and class-switch recombination (CSR) in B-cells. Acts via the formation of a heterodimer with JUNB that recognizes and binds DNA sequence 5'-TGA[CG]TCA-3'. The BATF-JUNB heterodimer also forms a complex with IRF4 (or IRF8) in immune cells, leading to recognition of AICE sequence (5'-TGAnTCA/GAAA-3'), an immune-specific regulatory element, followed by cooperative binding of BATF and IRF4 (or IRF8) and activation of genes. Controls differentiation of T-helper cells producing interleukin-17 (Th17 cells) by binding to Th17-associated gene promoters: regulates expression of the transcription factor RORC itself and RORC target genes such as IL17 (IL17A or IL17B). Also involved in differentiation of follicular T-helper cells (TfH) by directing expression of BCL6 and MAF. In B-cells, involved in class-switch recombination (CSR) by controlling the expression of both AICDA and of germline transcripts of the intervening heavy-chain region and constant heavy-chain region (I(H)-C(H)). Following infection, can participate in CD8(+) dendritic cell differentiation via interaction with IRF4 and IRF8 to mediate cooperative gene activation. Regulates effector CD8(+) T-cell differentiation by regulating expression of SIRT1. Following DNA damage, part of a differentiation checkpoint that limits self-renewal of hematopoietic stem cells (HSCs): up-regulated by STAT3, leading to differentiation of HSCs, thereby restricting self-renewal of HSCs (By similarity).
Synonyms: B-ATF; SFA-2; BATF1; SFA2
Tractability: No criterion of Open Targets' tractability assessment is met for any kind of drug.
Gene: Protein-coding gene on chromosome 14 (75,522,455 to 75,546,993, forward strand). Ensembl gene ENSG00000156127.
Subcellular location: Nucleus; Cytoplasm
Subcellular location (Human Protein Atlas): Nucleoplasm
Pathways (Reactome):
Developmental Biology: Differentiation of naive CD4+ T cells to T helper 2 cells (Th2 cells)
Immune System: Interleukin-4 and Interleukin-13 signaling
Gene Ontology:
Molecular function: protein binding; sequence-specific double-stranded DNA binding; DNA-binding transcription factor activity; DNA-binding transcription factor activity, RNA polymerase II-specific; RNA polymerase II cis-regulatory region sequence-specific DNA binding; sequence-specific DNA binding; DNA binding; DNA-binding transcription activator activity, RNA polymerase II-specific
Biological process: defense response to protozoan; DNA damage response; hematopoietic stem cell differentiation; integrated stress response signaling; isotype switching; lymphoid progenitor cell differentiation; myeloid dendritic cell differentiation; positive regulation of cytokine production; regulation of T-helper 17 cell differentiation; regulation of transcription by RNA polymerase II; T-helper 17 cell differentiation; T-helper 17 cell lineage commitment; T-helper 2 cell differentiation; positive regulation of transcription by RNA polymerase II; regulation of DNA-templated transcription
Cellular component: nucleoplasm; RNA polymerase II transcription regulator complex; chromatin; cytoplasm; nucleus
Genetic constraint (gnomAD): Loss-of-function variants: 5 observed, 14.23 expected, observed/expected ratio (o/e) 0.35, 90% interval 0.18 to 0.74. The upper end of that interval is the gene's LOEUF score, 0.74, which puts it in group 3 of 6, group 1 being the genes least tolerant of losing a copy. Missense variants: 124 observed, 171.38 expected, observed/expected ratio (o/e) 0.72, 90% interval 0.62 to 0.84. Synonymous variants: 72 observed, 72.83 expected, observed/expected ratio (o/e) 0.99, 90% interval 0.82 to 1.2.
Homologues: Orthologues: chimpanzee BATF (100% identical), dog BATF (97% identical), guinea pig BATF (97% identical), mouse Batf (96% identical), rabbit BATF (96% identical), rat Batf (96% identical), pig BATF (95% identical), macaque BATF (83% identical), zebrafish batf (63% identical), tropical clawed frog batf (53% identical), Drosophila melanogaster Atf3 (38% identical). Paralogues in human: BATF3 (45% identical), BATF2 (36% identical), FOS (34% identical), FOSL2 (33% identical), FOSB (30% identical), FOSL1 (30% identical), ATF3 (29% identical), JDP2 (27% identical).
Diseases named in the same sentence as BATF in open-access papers:
BATF is named in the same sentence as 86 diseases in open-access papers, as found by Europe PMC text mining. Sharing a sentence is not in itself a finding about the gene and the disease. The quoted sentences say what the papers report.
colitis (8 papers, 2018 to 2025). Inflammation of the colon. "Of interest, BATF is required for the expression of gut-homing receptors of T cells, and BATF-deficient T cells fail to induce colitis." (PMID 35514970, 2022). "RORγt was reported to represent the master regulator of Th17 cell differentiation, acts in concert with BATF in this pathway and cell type and its absence provides full protection in syngeneic colitis models in a manner comparable to BATF deficiency." (PMID 29910804, 2018). "Interestingly, we recently described that donor T cells lacking the expression of the Th17 lineage regulating transcription factor BATF indeed conferred protection against GvHD-associated colitis both in a major and minor histocompatibility mismatched model of allo-HSCT in mice." (PMID 29910804, 2018). "Additionally, in a colitis-associated cancer (CAC) model, BATF-deficient mice exhibited reduced tumor numbers and sizes, indicating that BATF-dependent IL-23R+IL-6+CD4+Th17 cells are pivotal in colitis-associated tumorigenesis." (PMID 39876010, 2025). "For example, circKcnt2 could inhibit the activation of group 3 innate lymphoid cells to facilitate colitis resolution, while its loop HR5 was required for the association between circKcnt2 and the BATF promoter." (PMID 38137460, 2023). "Mechanistically, BATF-deficient cells failed to accumulate within the intestines and induced pathology that is consistent with defects in BATF-deficient cells in inducing colitis." (PMID 32809971, 2020). "More importantly, under syngeneic conditions, RORγt- and BATF-deficient T cells comparably failed to induce colitis upon transfer into lymphopenic Rag1−/− mice." (PMID 29910804, 2018). "In a T-cell transfer model of colitis, Th17 cells deficient in BATF failed to induce IBD." (PMID 39876010, 2025). "Studies using a dextran sulfate sodium-induced colitis mouse model have identified numerous IL-17+neutrophils that promote disease progression via an IL-23 and STAT3-dependent RORγT and BATF pathway." (PMID 39876010, 2025). "However, given our findings that acute GvHD-associated colitis depends on donor T cell-intrinsic BATF but not RORγt expression, we sought to further explore how Batf expression in the inflamed colon relates to the presence of RORγt- and BATF-expressing donor T cells, respectively." (PMID 29910804, 2018). "The nuclear circRNA CircKcnt2 inhibits BATF expression by recruiting the NuRD complex to the BATF promoter, thereby suppressing IL-17 expression and reducing ILC3 activity, aiding in the resolution of innate colitis." (PMID 39876010, 2025).
lymphoma (8 papers, 2014 to 2025). A malignant (clonal) proliferation of B- lymphocytes or T- lymphocytes which involves the lymph nodes, bone marrow and/or extranodal sites. "BATF/BATF3 are important for expression of genes in ALK+ ALCL that are associated with the TH17/group 3 innate lymphoid cell gene signature observed in this lymphoma." (PMID 33413671, 2021). "For instance, BATF has been studied extensively in lymphoma and melanoma and is known to regulate T helper (Th) cell differentiation and immune responses." (PMID 39559348, 2024). "Here, we identified BATF as a top upregulated gene at the mRNA level in lymphoma cells inducibly expressing MyD88L265P." (PMID 36982699, 2023). "We detected a significant enrichment of c-FOS, FOSL1, FOSL2, c-JUN, and BATF target genes in H3K27ac ChIP–seq peaks upregulated in ITK–SYK+PD-1− lymphoma cells compared to their premalignant ITK–SYK+PD-1+ counterparts." (PMID 37723306, 2023). "The BATF gene acts a pivotal part in the development of different types of cancer, including colon cancer, lymphoma, and multiple myeloma." (PMID 32733620, 2020). "In conclusion, the data presented here define the relationship of IRF4 to its endogenous partners in ABC-DLBCL cell lines identifying BATF as a principle IRF4 partner in addition to SPIB in these models of lymphoma." (PMID 24875472, 2014). "According to some studies, BATF may play a role in the development and progression of certain types of cancer, including leukemia and lymphoma." (PMID 36982699, 2023). "However, more research is needed to understand BATF regulation and function in lymphoma." (PMID 36982699, 2023). "The chronic stimulation by lymphoma results in T cell exhaustion driven by transcription factors such as TOX, EOMES, BATF, and IRF4, which is further affected by the immunosuppressive microenvironment and more lines of therapy." (PMID 40248244, 2025). "The elevated expression of several AP-1 proteins including c-Jun, JunB, ATF3, BATF, and BATF3 has also been described in CD30-positive lymphomas." (PMID 33413671, 2021). "We employed machine learning algorithms to screen six genes, BATF, CXCR3, GIMAP5, GPR8, IGHM, and ISG20, that have been extensively investigated in other cancers, including lymphoma, melanoma, leukemia, breast cancer, multiple myeloma, hepatocellular carcinoma, and lung cancer." (PMID 39559348, 2024). "A series of studies suggest that BATF may influence the development of different types of cancer, including non-small cell lung cancer (NSCLC), lymphoma, and multiple myeloma." (PMID 34178621, 2021).
autoimmune disease (7 papers, 2019 to 2025). A disorder resulting from loss of function or tissue destruction of an organ or multiple organs, arising from humoral or cellular immune responses of the individual to their own tissue constituents. "Lines of evidence indicate that BATF is associated with the onset and progression of allergic diseases, graft-versus-host disease, tumors, and autoimmune diseases." (PMID 39876010, 2025). "A TREG-specific BATF deficiency in mice (Foxp3CREBatffl/fl; BATF-/-), results in a multiorgan autoimmune disease with death initiating at 6 weeks of age." (PMID 38605970, 2024). "TFs tightly control cell fate in immune cells and have been implicated in the pathogenesis of autoimmune diseases, such as BATF in arthritis and PU.1 in systemic lupus erythematosus." (PMID 37848613, 2023). "Our study further reveals that the genomic binding sites of FOSL1, FOSL2 and BATF harbour hundreds of autoimmune disease-linked SNPs." (PMID 35511484, 2022). "Additionally, the expression levels of BATF and its family members are associated with autoimmune diseases, suggesting that they may serve as potential disease biomarkers or diagnostic tools to aid for early diagnosis and prognosis evaluation." (PMID 39876010, 2025). "This review summarizes the research progress in elucidating the roles of BATF in regulating immune cell differentiation and function, with a particular focus on its implication in the development of autoimmune diseases." (PMID 39876010, 2025). "BATF contributes to the progression of autoimmune diseases by regulating the differentiation and function of Th17, Tfh, Treg, and B cells." (PMID 39876010, 2025). "Considering its role in Treg stability, BATF should be considered an important therapeutic target in autoimmune disease." (PMID 37587835, 2023). "Understanding the role of BATF in Treg maintenance and stability is a prerequisite to the design of strategies that enhance Treg function and therapeutic efficacy in autoimmune diseases and organ transplantation." (PMID 37587835, 2023). "We identified hundreds of autoimmune disease-associated SNPs within the genomic-binding sites of FOSL1, FOSL2 and BATF." (PMID 35511484, 2022). "Both the functions and regulatory mechanisms of BATF exhibit complex characteristics in the pathogenesis of autoimmune diseases, exhibiting a key role in disease onset and progression by regulating immune cell function, immune tolerance, and inflammatory responses." (PMID 39876010, 2025). "In summary, BATF plays a critical role in the pathogenesis of these autoimmune diseases and may serve as a potential therapeutic target by inhibiting the activation of autoreactive cells to mitigate disease progression." (PMID 39876010, 2025). "Further investigation into the structure and function of BATF, as well as its role in autoimmune disease development, may facilitate the identification of potential therapeutic targets for the treatment of autoimmune diseases." (PMID 39876010, 2025). "However, the BATF-mediated molecular pathways involved in autoimmune diseases are only partially elucidated." (PMID 39876010, 2025). "For example, H3K27ac regions containing autoimmune-disease-prioritized variants were linked to the TSS of genes using HiChIP and shown to contain cell-type-specific interactions between the TSS of the IL2 gene and rs7664452 in Th17 cells and between rs2300604 and target gene BATF in memory T cells." (PMID 31937202, 2020). "Current studies on how BATF specifically regulates autoimmune diseases is mainly focused on molecular mechanisms and has not yet been widely applied in clinical trials." (PMID 39876010, 2025). "We previously tested whether genes coregulated by the “Th17 core” (RORC, STAT3, BATF, IRF4, and MAF) were enriched for gene sets from GWAS of nine autoimmune diseases and three “negative controls” (Alzheimer's, schizophrenia, and type 2 diabetes)." (PMID 30696696, 2019).
viral infection (7 papers, 2019 to 2025). "Among the 6 genes, over-expressed genes (HK3, DEFA4, BATF) were positively correlated with severity of viral infection, and under-expressed genes (HLA-DPB1, LY86, TGFBI) were negatively correlated with severity." (PMID 35042868, 2022). "BATF expression is increased in exhausted T cells during chronic viral infection in humans and in mice." (PMID 31044512, 2019). "Interestingly, some other research also indicates that elevated BATF expression can enhance T cell effector functions in both chronic and acute viral infections." (PMID 40093905, 2025). "In viral infection models, chronic HIV infection has been shown to elevate BATF expression in T cells, leading to exhaustion and impairing the body's antiviral response." (PMID 40093905, 2025). "In addition, human corneal naive T cells highly expressed BATF, which has been proven to be crucial for the differentiation of effector CD8+ T cells in a steady state and during viral infection." (PMID 35280984, 2022). "Each of the 6 genes were significantly differentially expressed between patients with viral infections who survived and those who did not, of which 3 genes (DEFA4, BATF, HK3) were higher and 3 genes (TGFBI, LY86, HLA-DPB1) were lower in those who died." (PMID 35042868, 2022).
breast carcinoma (6 papers, 2017 to 2025). "Hence, in this study, we investigated the effects of calycosin on breast cancer cell progression and the underlying mechanisms, including its effect on BATF expression and functions in breast cancer cells." (PMID 34096887, 2021). "In this study, we demonstrated that calycosin reduced BATF protein levels in breast cancer cells in a concentration-dependent manner." (PMID 34096887, 2021). "In summary, our data demonstrated that calycosin inhibited in vitro migration, invasiveness and growth of breast cancer cells by suppressing BATF/ TGFβ1." (PMID 34096887, 2021). "Wound healing and Transwell invasion assays showed that breast cancer cell migration and invasiveness was significantly increased by BATF overexpression and significantly reduced by BATF silencing." (PMID 34096887, 2021). "Calycosin dose- and time-dependently inhibited proliferation, migration, and invasion by T47D and MCF-7 breast cancer cells by downregulating basic leucine zipper ATF-like transcription factor (BATF) expression." (PMID 34096887, 2021). "Wound healing assay results showed that TGFβ1 knockdown significantly reduced the migration of BATF-overexpressing breast cancer cells compared to the corresponding controls." (PMID 34096887, 2021). "The levels of CD147, MMP-2 and MMP-9 transcripts and proteins were significantly increased in BATF-overexpressing breast cancer cells and significantly reduced in BATF-silenced breast cancer cells." (PMID 34096887, 2021). "We observed that overexpression of BATF upregulated TGFβ1 mRNA and protein levels in breast cancer cells, whereas, TGFβ1 knockdown decreased BATF mRNA and protein levels in BATF-overexpressing breast cancer cells." (PMID 34096887, 2021). "We then analyzed if calycosin suppressed invasion and migration of BATF-overexpressing breast cancer cells." (PMID 34096887, 2021). "Our findings demonstrated that calycosin inhibited EMT and progression of breast cancer cells by suppressing BATF/TGFβ1 signaling." (PMID 34096887, 2021). "Calycosin treatment significantly downregulated the levels of BATF and TGFβ1 transcripts and proteins in breast cancer cells." (PMID 34096887, 2021). "In summary, our results demonstrated that calycosin inhibited breast cancer cell progression by suppressing EMT via BATF/TGFβ1." (PMID 34096887, 2021). "Moreover, BATF promoted breast cancer cell migration and invasiveness by increasing TGFβ1 mRNA and protein levels." (PMID 34096887, 2021). "Furthermore, TGFβ1 mRNA and protein levels were significantly increased by BATF overexpression and significantly reduced by BATF knockdown in breast cancer cells." (PMID 34096887, 2021). "Therefore, we analyzed the effects of BATF overexpression or knockdown on in vitro breast cancer cell migration and invasiveness." (PMID 34096887, 2021). "Moreover, BATF overexpression increased migration and invasiveness of breast cancer cells." (PMID 34096887, 2021). "RT-qPCR and western blot analyses showed that calycosin treatment downregulated BATF mRNA and protein levels in T47D and MCF-7 breast cancer cells." (PMID 34096887, 2021). "Calycosin treatment inhibited epithelial-mesenchymal transition (EMT) of breast cancer cells by significantly increasing E-cadherin levels and decreasing N-cadherin, Vimentin, CD147, MMP-2, and MMP-9 levels through downregulation of BATF and TGFβ1." (PMID 34096887, 2021). "BATF mRNA and protein levels were significantly upregulated in BATF-overexpressing T47D and MCF-7 breast cancer cells and downregulated in si-BATF-transfected T47D and MCF-7 breast cancer cells." (PMID 34096887, 2021). "We find that high expression of BATF (P = 0.0035) and TP73 (P = 0.0077) is correlated with breast cancer patient survival in HER2+ and Basal-like subtypes, respectively." (PMID 28957321, 2017).
leukemia (5 papers, 2014 to 2024). A malignant (clonal) hematologic disorder, involving hematopoietic stem cells and characterized by the presence of primitive or atypical myeloid or lymphoid cells in the bone marrow and the blood. "First, we established an AML mouse model by injecting C57BL/6 mice with GFP+ murine leukemia C1498 cells overexpressing BATF or control cells, followed by treatment with cytarabine and venetoclax." (PMID 39872530, 2024). "In addition, the qRT-PCR and Western blotting results also showed that BATF was overexpressed in leukaemia cell lines compared to control cells, especially in the THP-1 and MOLM-13 cell lines." (PMID 39872530, 2024). "BATF or JUN mediated enhanced leukemia clearance in our model independent of starting cell state, indicating that these TFs may derive most of their early in vivo activity via binding to NFAT-AP1 composite motifs, which show high accessibility in both cell types." (PMID 38196657, 2023).